TBXAS1 (thromboxane A synthase 1)
Description:
Catalyzes the conversion of prostaglandin H2 (PGH2) to thromboxane A2 (TXA2), a potent inducer of blood vessel constriction and platelet aggregation. Also cleaves PGH2 to 12-hydroxy-heptadecatrienoicacid (12-HHT) and malondialdehyde, which is known to act as a mediator of DNA damage. 12-HHT and malondialdehyde are formed stoichiometrically in the same amounts as TXA2. Additionally, displays dehydratase activity, toward (15S)-hydroperoxy- (5Z,8Z,11Z,13E)-eicosatetraenoate (15(S)-HPETE) producing 15-KETE and 15-HETE.
Synonyms: TXS; CYP5; CYP5A1; TXAS; THAS; TS; BDPLT14; GHOSAL
Tractability: Small molecule: an approved drug acts on it; a high-quality ligand is known; it belongs to a druggable protein family. Antibody: UniProt predicts a signal peptide or a membrane-spanning region. PROTAC: its protein half-life has been measured; a small molecule that binds it is known.
Target class: Cytochrome P450 family 5A; Cytochrome P450 family 5; Enzyme; Cytochrome P450 5A1; Cytochrome P450
Safety:
Unwanted effects reported when the protein is acted on. In parentheses: how it was acted on, where the effect was seen, and who reports it.
aspirin-intolerant asthma (source: ClinPGx)
Gene: Protein-coding gene on chromosome 7 (139,777,051 to 140,020,325, forward strand). Ensembl gene ENSG00000059377.
Subcellular location: Endoplasmic reticulum membrane
Subcellular location (Human Protein Atlas): Cytosol; Endoplasmic reticulum
Pathways (Reactome):
Metabolism: Eicosanoids; Synthesis of Prostaglandins (PG) and Thromboxanes (TX)
Disease: Defective TBXAS1 causes GHDD
Gene Ontology:
Molecular function: 12-hydroxyheptadecatrienoic acid synthase activity; heme binding; hydroperoxy icosatetraenoate dehydratase activity; protein binding; thromboxane-A synthase activity; iron ion binding; monooxygenase activity; oxidoreductase activity, acting on paired donors, with incorporation or reduction of molecular oxygen
Biological process: icosanoid metabolic process; prostaglandin biosynthetic process; prostanoid biosynthetic process; fatty acid metabolic process; intracellular chloride ion homeostasis; positive regulation of vasoconstriction; response to ethanol; response to fatty acid
Cellular component: endoplasmic reticulum; endoplasmic reticulum membrane; endoplasmic reticulum lumen
Genetic constraint (gnomAD): Loss-of-function variants: 48 observed, 64.43 expected, observed/expected ratio (o/e) 0.75, 90% interval 0.59 to 0.95. The upper end of that interval is the gene's LOEUF score, 0.95, which puts it in group 4 of 6, group 1 being the genes least tolerant of losing a copy. Missense variants: 685 observed, 721.09 expected, observed/expected ratio (o/e) 0.95, 90% interval 0.89 to 1.01. Synonymous variants: 287 observed, 283.27 expected, observed/expected ratio (o/e) 1.01, 90% interval 0.92 to 1.12.
Gene-disease validity (ClinGen):
ClinGen rates the evidence that TBXAS1 causes each of these diseases.
ghosal hematodiaphyseal dysplasia (autosomal recessive): Definitive. Ghosal hematodiaphyseal dysplasia syndrome (GHDD) is a rare disorder characterized by increased bone density (predominantly diaphyseal) and aregenerative corticosteroid-sensitive anemia.
Homologues: Orthologues: chimpanzee TBXAS1 (99% identical), macaque TBXAS1 (97% identical), dog TBXAS1 (82% identical), pig TBXAS1 (82% identical), mouse Tbxas1 (82% identical), rat Tbxas1 (80% identical), guinea pig TBXAS1 (79% identical), rabbit TBXAS1 (76% identical), tropical clawed frog tbxas1 (55% identical), zebrafish tbxas1 (49% identical).
Diseases named in the same sentence as TBXAS1 in open-access papers:
TBXAS1 is named in the same sentence as 71 diseases in open-access papers, as found by Europe PMC text mining. Sharing a sentence is not in itself a finding about the gene and the disease. The quoted sentences say what the papers report.
breast carcinoma (10 papers, 2005 to 2024). "In the literature, lower TBXAS1 expression was associated with higher grade and poor prognosis of breast cancer patients." (PMID 33802237, 2021). "However, TBXAS1 polymorphisms have shown a modest association with breast cancer risk and poor outcomes." (PMID 36234768, 2022). "However, TBXAS1 polymorphisms are moderately associated with breast cancer risk and poor outcomes." (PMID 39720182, 2024). "In breast cancer, there is controversy about the correlation between TBXAS1 expression and tumor grading, with one study showing that expression is lost with increasing grade, but there are also opposite reports." (PMID 39720182, 2024). "In the early years, researches on TBXAS1 gene mainly focused on inflammation, breast cancer, and other diseases." (PMID 35923246, 2022). "In breast cancer, there is dissent over the correlation of TBXAS1 expression and tumor grade, with one study suggesting loss of expression with increasing grade but the reverse has also been reported." (PMID 36234768, 2022). "During the immunohistochemical study, we noticed that positive regions of TBXAS1 or TBXA2R immunostaining were mainly in mammary ducts from where primary breast cancer is believed to arise." (PMID 29872696, 2017). "To clarify the importance of the TXA2 pathway in breast cancer, we first examined the expression of TBXAS1, a rate-limiting enzyme coupled with COXs in the synthesis of TXA2." (PMID 29872696, 2017). "The positive regions of TBXAS1 immunostaining were mammary ducts from where primary breast cancer is believed to arise." (PMID 29872696, 2017). "By using an MMTV-Her2/neu transgenic mouse mammary tumor model, we established that TBXAS1 and HER2 were co-overexpressed and co-localized in the mammary ducts." (PMID 29872696, 2017). "To further characterize the role of the TXA2 pathway in breast cancer, we successfully established TBXAS1-overexpressing stable sub-clones from murine mammary carcinoma 4T1cells, which expressed very low levels of endogenous TBXAS1." (PMID 29872696, 2017). "The intricate interplay of TBXAS1 and LRP1 influences cancer gene expression, while TBXAS1’s elevated levels in poor-prognosis breast cancer samples suggests a parallel lung cancer implications for LUSC." (PMID 38389572, 2024). "The aim of the study was to investigate the expression of thromboxane synthases, TBXAS1 and the thromboxane A2 receptor, TBXA2R in a cohort of human breast cancer patients and also to assess their potential clinical relevance." (PMID 16250911, 2005). "In the current study, we have investigated the level of expression of Thromboxane A synthase 1, TBXAS1 (otherwise known as Cyp5 and TXS) and Thromboxane A2 receptor, TBXA2R, in a cohort of human breast cancer patients." (PMID 16250911, 2005). "However, data in breast cancer patients are less clear, with TXA2S expressed at significantly lower levels in patients with high grade tumors with poor prognostic outcome in one study but high TBXAS1 expression correlated with invasive disease and higher tumor grades in another." (PMID 36234768, 2022).
asthma (6 papers, 2018 to 2024). "In AERD vs. asthma, we detected 4 SNPs associated in three genes: TBXAS1 rs2269997 CC p = 0.002, OR = 2.67, CI 95% = 1.40–5.0 (CM), and p = 0.02, OR = 1.96, CI 95% = 1.13–3.34 (RM)." (PMID 30254660, 2018). "Likewise, a rare allele (rs6962291) in the TBXAS1 gene was associated with lower catalytic activity and was protective in aspirin-intolerant asthma in a Korean population." (PMID 38483511, 2024). "Expression of TBXAS1 is pharmacogenomic linked to inhaled GC exposure in asthma." (PMID 33821793, 2021). "In addition, these observations raise the possibility that polymorphisms in the TBXAS1 or the TBXA2R gene may be associated with altered asthma risk in humans." (PMID 38483511, 2024). "In the last comparison asthma vs. control group we detected seven SNPs in four genes (TBXAS1, FANCC, CYSLTR2, and PTGER3)." (PMID 31936183, 2020). "Finally, in the asthma vs. HC comparison, 9 SNPs were identified, with 2 associated with risk in the MS4A2 gene (rs573790 p = 0.001, OR = 1.70, CI 95% = 1.21-2.37), and 7 SNPs associated with protection in 4 genes (TBXAS1, FANCC, CYSLTR2, and PTGER3)." (PMID 30254660, 2018). "In addition to THSD4 and HIVEP2, age-by-genotype interactions also prioritized genes previously identified as asthma candidate genes, including DPP10, HDAC9, TBXAS1, FBXL7, and GSDMB/ORMDL3, as pharmacogenomic loci as well." (PMID 32119686, 2020). "When comparing asthma vs. CG TBXAS1-rs13239058, FANCC-rs1326188 and OBSCN-rs465344 obtained p < 0.02 in the codominant model, TBXAS1-rs13239058CC had statistical significance in the dominant model p = 0.02, OR = 0.61, FANCC-rs132618AA p = 0.007, OR = 0.48, and OBSCN-rs465344GG p = 0.004, OR = 2.16." (PMID 31936183, 2020). "For TBXAS1 rs757760, MS4A2 rs502581, IL10 rs3024498, and ACE (rs4293 and rs4309), we did not detect any statistical association comparing AERD vs. asthma/HC or asthma vs. HC, in the allelic, recessive and codominant models (p > 0.05)." (PMID 30254660, 2018).
bladder cancer (5 papers, 2010 to 2024). "The results showed that TBXAS1 was significantly associated with patient prognosis in bladder cancer, low-grade glioma, hepatocellular carcinoma and squamous cell carcinoma." (PMID 39720182, 2024). "In bladder cancer cells, pharmacologic inhibition of TBXAS1 with furegrelate or ozagrel induced apoptosis and enhanced sensitivity to chemotherapy, which does suggest that pharmacologic inhibition of this enzyme has potential for treatment in AML." (PMID 20209125, 2010). "Few studies had reported that the six genes (TBXAS1, GYPC, HPGDS, GAB3, ADORA3, and FOLR2) had strong correlation with bladder cancer." (PMID 36275756, 2022).
lung carcinoma (5 papers, 2011 to 2024). "While TBXAS1 is functionally quite different from the other candidates, changes in TBXAS1 expression in lung cancer cell lines have been associated with increased ROS production and induction of apoptosis, a finding that was negated when treated with antioxidant treatment." (PMID 23766848, 2013).
Stroke (5 papers, 2013 to 2024). Sudden impairment of blood flow to a part of the brain due to occlusion or rupture of an artery to the brain. "TBXAS1 protein has been reported to be strongly associated with pathophysiological processes, including hemostasis, cardiovascular disease, and stroke." (PMID 39720182, 2024). "Data from the literature also evidenced the association of thromboxane A synthase 1 gene expression and promotor haplotypes with the risk of large artery-atherosclerosis stroke in the Iranian population." (PMID 39035772, 2024). "It was reported that TBXAS1 protein had strong correlation with pathophysiological processes including hemostasis, cardiovascular disease, and stroke." (PMID 36275756, 2022). "TBXAS1 gene is located to 7q34-q35 and has been related with the physiopathology of a number of diseases including cerebral infarction, myocardial infarction and stroke." (PMID 24086445, 2013).
colorectal cancer (3 papers, 2011 to 2023). A primary or metastatic malignant neoplasm that affects the colon or rectum. "The knockdown of TBXA2R (TP receptor) or TBXAS1 (TXS) in human colorectal cancer cells results in fewer colonies being formed in soft agar than in control cells." (PMID 37173923, 2023). "Based on this idea, we confirmed that knockdown of TBXA2R or TBXAS1 in human colorectal cancer cells resulted in fewer colonies being formed in soft agar compared with control cells." (PMID 25750933, 2015).
ghosal hematodiaphyseal dysplasia (3 papers, 2011 to 2025). "However, this patient carrying the TBXAS1 p.Thr348Ile variant is the first described in the literature with a history of significant bleeding and without the classic characteristics of Ghosal syndrome." (PMID 41463295, 2025).
melanoma (3 papers, 2021 to 2022). A malignant, usually aggressive tumor composed of atypical, neoplastic melanocytes. "Based on the FAM molecular subtypes, we identified the 6 FAMGs (ACSL5, ALOX5AP, CD1D, CD74, IL4I1, TBXAS1) that play vital regulatory roles in the melanoma TME." (PMID 36466837, 2022). "Mutation frequency of TBXAS1, PTGIS, AKR1C3, PTGDR, PTGFR and PTGER3 genes in melanoma were 5–6%, 5–7%, 2.8–5%, 3–4%, 7–9%, 2.1–5%, respectively." (PMID 35453789, 2022). "muTARGET web-based tool allowed us to predict genes, which expression patterns can be associated with genetic polymorphism in group #1 (TBXAS1, PTGIS, and AKR1C3) or group #2 (PTGDR, PTGFR, and PTGER3) in melanoma." (PMID 35453789, 2022).
myocardial infarction (3 papers, 2013 to 2024). Gross necrosis of the myocardium, as a result of interruption of the blood supply to the area, as in coronary thrombosis. "TBXAS1, the gene coding for TBX synthase has been associated with increased myocardial infarction (MI) risk, changes in platelet function and carotid plaque vulnerability." (PMID 39062733, 2024).
prostate carcinoma (3 papers, 2011 to 2024). A carcinoma that arises from epithelial cells of the prostate gland. "In prostate cancer, TBXAS1 expression is associated with the severity of prostate cancer lesions, with the highest levels in advanced and poorly differentiated forms." (PMID 39720182, 2024). "In prostate cancer, TBXAS1 expression is correlated with the severity of prostate carcinoma lesions, with advanced stages and poorly differentiated forms having the highest expression levels." (PMID 36234768, 2022).
bleeding diathesis (2 papers, 2019 to 2025). "And finally, TBXAS1 variants in heterozygosis can lead to bleeding diathesis." (PMID 41463295, 2025). "Although TBXAS1 alterations were thought to be responsible for a mild bleeding disorder, none of the described patients with GHDD reported bleeding manifestations." (PMID 41463295, 2025).
breast tumors (2 papers, 2017 to 2022). "6, 18 Our immunohistochemical data confirmed that TBXAS1 expression in breast tumors was 4.6-fold higher than observed in normal adjacent tissues (NAT)." (PMID 29872696, 2017). "The knockdown of TBXAS1 (the rate-limiting enzyme involved in TXA2 biosynthesis) and TBXA2R (TXA2 receptor) both of which are overexpressed in breast tumours, reduced the colony formation and proliferation of hormone-dependent breast tumour cell lines." (PMID 36558983, 2022).
colon cancer (2 papers, 2015 to 2019). "Knockdown of either TBXAS1 or TBXA2R impairs the anchorage-independent growth capability of colon cancer cells." (PMID 25750933, 2015). "In addition, aspirin treatment down-regulated TBXA2R or TBXAS1 expression in colon cancer cells." (PMID 25750933, 2015).
ischemic stroke (2 papers, 2017 to 2022). A stroke disorder caused by obstruction of blood flow to the brain, due to thrombotic (local blood clot formation) or embolic (due to a blood clot or other material traveling from another site) event. "In the present study, results demonstrate that TBXAS1 gene NC_000007.14:g.139985896C>T polymorphism was related to the incidence of ischemic stroke in patients with MS." (PMID 35923246, 2022). "A study of Chinese people found that the TT genotype of TBXAS1 and T allele of NC_000007.14:g.139845571 T > G increase susceptibility to ischemic stroke." (PMID 35923246, 2022). "Up to date, the association of TBXAS1 variation with cardiovascular disease and ischemic stroke has not been well addressed." (PMID 28704403, 2017).
squamous cell carcinoma (2 papers, 2011 to 2024). A carcinoma arising from squamous epithelial cells. "TBXAS1 consistently promoted poor prognosis in all tumors except squamous cell carcinoma, which was consistent with the previous results that TBXAS1 was highly expressed in most tumor tissues." (PMID 39720182, 2024).
Alzheimer disease (1 paper, 2024). A progressive, neurodegenerative disease characterized by loss of function and death of nerve cells in several areas of the brain leading to loss of cognitive function such as memory and language. "The presence of the CACNA2D3 (0.938, 0.902 − 0.975, P = .001), INPP5D (0.844, 0.802 − 0.888, P < .001), RBM47 (0.937, 0.891 − 0.985, P = .011) and TBXAS1 (0.965, 0.934 − 0.998, P = .036) may be associated with a lower risk of Alzheimer’s disease." (PMID 39560568, 2024).
aortic valve disease (1 paper, 2024). "Additionally, AS from LVH demonstrates upregulated anti-inflammatory COX receptor-related genes PTGER2 and PTGER4, and LOX-derived LT receptor-related gene CYSLTR2, but downregulated TBXAS1 and ALOX5, suggesting different mechanisms causing aortic valve disease and aortic calcification." (PMID 39062733, 2024).
breast adenosis (1 paper, 2017). A non-neoplastic disorder characterized by epithelial and/or myoepithelial tissue growth in the breast lobules. "Interestingly, TBXAS1 expression was also more likely to increase in breast precancerous lesions such as breast adenosis, epithelium hyperplasia and atypical ductal hyperplasia." (PMID 29872696, 2017).
cardiac arrhythmia (1 paper, 2023). Any disturbances of the normal rhythmic beating of the heart or MYOCARDIAL CONTRACTION. "The thromboxane A2 (TxA2) encoded by TBXAS1 plays a detrimental role in the cardiovascular system because it induces platelet aggregation, vascular dysfunction, vasoconstriction, and even cardiac arrhythmias." (PMID 37372445, 2023).
congenital heart disease (1 paper, 2017). A heart disease that is present at birth. "Variations in NOTCH2, NOTCH3, TTN, TBX4, TBX10, TBX18, and TBXAS1 are associated with congenital heart disease." (PMID 29381953, 2017).
depression (1 paper, 2024). "Significant associations between rs6945590 or TBXAS1 expression and the risk of depressive symptoms or depression were found in at least two independent cohorts." (PMID 38320993, 2024). "Considering that TXA2 activates the immune response, which may be positively associated with the risk of depression, it appears that the risk of depressive symptoms may decrease with the decrease in TBXAS1 expression." (PMID 38320993, 2024). "Among symptoms of depression, lack of satisfaction and sleep disturbance were highly associated with rs6945590 and TBXAS1." (PMID 38320993, 2024). "Further studies with larger sample sizes are needed to fully understand the genetic mechanism of depression and to determine whether TBXAS1 could be used as a blood marker or target for treating depression." (PMID 38320993, 2024).
malignant mesothelioma (1 paper, 2022). A malignant neoplasm of the pleura or peritoneum, arising from mesothelial cells. "A study of malignant mesothelioma conducted by Daisuke found that TBXAS1 gene expression was down-regulated in rats with iron-induced mesothelioma, and iron overload was associated with TBXAS1 down-regulation." (PMID 35205354, 2022).